CXCL2 (C-X-C motif chemokine ligand 2)
Diseases named in the same sentence as CXCL2 in open-access papers (continued):
Sharing a sentence is not in itself a finding about the gene and the disease.
tumor (continued). "In BC, tumor cells induced MDSC aggregation and expansion in the TME via the CXCL2/MIF-CXCR2 signaling pathway and the elevated phosphorylation of p38, ERK, and p65." (PMID 33981768, 2021). "The chemokine receptor CXCR2 and its ligands CXCL1, CXCL2, CXCL3, CXCL5 and CXCL8 play critical roles in the chemoattraction of neutrophils towards tumor tissues." (PMID 34429454, 2021). "CXC chemokine ligand 2 (CXCL2), also referred to as macrophage inflammatory protein-2 (MIP-2), has a pivotal role in recruiting MDSCs to tumor stroma." (PMID 32391020, 2020). "Myeloid-derived suppressor cells (MDSC) expressing CXCR2 can be recruited to the developing tumor by CXCL1 and CXCL2, possibly induced by PGE2." (PMID 32276475, 2020). "During the formation of the tumor metastasis microenvironment, increased secretion of CXCL1 and CXCL2 by endothelial cells and megakaryocytes promotes the release of neutrophils into circulation via the regulation of CXCR2 signaling." (PMID 33363026, 2020). "Other members of the ELR+ CXC chemokine family, CXCL1 and CXCL2 were found to be induced in normal mammary fibroblasts that gained a CAF phenotype in response to tumor cell-derived osteopontin, that also promoted tumor growth." (PMID 32582148, 2020). "Hypoxia induced expression of CXCL1 (GRO-α), CXCL2 (MIP2α), CXCL5 (LIX) recruited anti-tumor neutrophils, which inhibited tumor growth by inducing tumor cell detachment from the basement membrane." (PMID 33262763, 2020). "As demonstrated in a mouse model, MDSC migration toward tumor tissue takes place by chemotaxis and depends on chemokines such as CXCL1 and CXCL2." (PMID 32488850, 2020). "In fact, neutrophils extravasate the blood and recruit into tumor tissue in response to cytokines (IFN-γ and TNF-α), chemokines (KC/CXCL1 and MIP2α/CXCL2 in mice) and cell adhesion molecules (i.e., CD11b)." (PMID 32499786, 2020). "Reversely, the chemokine receptor CXCR2 and its ligands CXCL1, CXCL2, and CXCL5 play an important role in homing of neutrophils to cancer cells to limit tumor growth." (PMID 33105656, 2020). "These molecules included a chemokine CXCL2 as well as the ligand VEGF-C, a proangiogenic factor actively released by the tumor cells for the formation of new vessels." (PMID 32848147, 2020). "In contrast, increased serum levels of chemokines CXCL1 and CXCL2 in mice correlated with increasing levels of CXCR2-expressing neutrophils in the blood and enhanced melanoma growth, with tumor growth being reduced by antibody-mediated blocking of CXCR2." (PMID 33105656, 2020). "In order to determine the mechanism of neutrophils recruitment into the tumour, we screened neutrophil attracting chemokines (CXCL1, CXCL2, CXCL3, CXCL5, CXCL8 and CXCL12)." (PMID 32778818, 2020). "In an orthotopic tumour model using SCID mice, omentectomy suppressed GC growth and peritoneal dissemination, and reduced serum levels of CXCL2." (PMID 32439934, 2020). "To gain further insight on the molecular mechanism mediating gMDSC recruitment to BCM-2277 tumors, we then treated a cohort of tumor-bearing mice with an inhibitor of CXCR2, the receptor through which CXCL1 and CXCL2 signal." (PMID 32634121, 2020). "Neutrophils can have significant anti-tumor activity Expression of CXCL1, CXCL2, and CXCL5 chemokine driven by hypoxia within the tumor microenvironment cause neutrophil recruitment to the tumor site." (PMID 32824655, 2020). "Among the chemokine ligands, CXCL1, CXCL2, CXCL6, and CXCL9 genes also displayed a higher expression in tumors with BD3 compared to low-grade tumor budding." (PMID 32719800, 2020). "Measurements of 36 different chemokines in the culture medium revealed a significant decrease in the secretion of CCL5, CCL8, CXCL1, CXCL2, CXCL5, and TGFβ1 and a significant increase in TGFβ2 secretion by TB9-Fhit transfected tumor cells." (PMID 32545680, 2020).
tumor (continued). "The expression of CXCL1, CXCL2, CXCL5, and CXCL8, which are CXCR2 ligands, and the expression of KITL and GM-CSF are strongly enhanced by KRAS signaling in cancer cells and tumor-derived hypoxia." (PMID 31474975, 2019). "Overexpression of CXCL2 or CCL22, or depletion of CD8a, impaired ttIL-12’s efficacy in suppressing tumor growth and metastasis, which validated the novel mechanism of ttIL-12 in converting a short OS immune profile to a long OS immune profile." (PMID 31208461, 2019). "The chemokines CXCL1, CXCL2, CXCL5, CXCL6, and CXCL8 secreted from tumor cells attract neutrophils in the blood to the tumor microenvironment via CXCR1 and CXCR2 on the surface of neutrophils." (PMID 30736371, 2019). "In this model, the authors were able to show that the CXCR2 ligands CXCL2 and CXCL5 are differentially expressed in tumor and stromal cells." (PMID 31561620, 2019). "RNAseq analysis showed that CDK2i- and EZH2i-upregulated genes were enriched in the chemokine/cytokine pathways, such as TNFA, CXCL2, and CCL20, which affect the tumor microenvironment." (PMID 31704972, 2019). "Three fractions of RT increased the concentrations of seven inflammatory mediators in tumor tissues: GM-CSF, IL-17, CXCL1, CXCL2, CCL2, CCL5 and TNFα." (PMID 31752313, 2019). "IL-17 in the K-ras mutant LUAD microenvironment induces epithelial secretion of CXCL2 and G-CSF to recruit neutrophils to the TME and exert their tumor-promoting functions." (PMID 32039025, 2019). "The cells traffic through the circulation and are chemoattracted to the tumor microenvironment by a series of chemokines such as CCL2 and CXCL2 that are present in the tumor microenvironment." (PMID 31001479, 2019). "Experimental murine studies and clinical correlation analyses have identified ligands for CXCR2 as major drivers of TAN recruitment into tumor lesions, involving CXCL1/KC, CXCL2/MIP-2, CXCL5/LIX, CXCL6, and MIF." (PMID 31293583, 2019). "Consistent with pathological features, there was significantly higher expression of cytokines IL-6 (Il6) and TNFα (Tnfa), chemokines KC (Cxcl1), MIP2 (Cxcl2), and MCP1 (Ccl2), and tumor-promoting molecule COX2 (Cox2) in Nlrp12-/- HCC." (PMID 30990169, 2019). "Neutrophils are recruited at the tumor sites by several chemokine signals, such as CXCL12, CXCL8, CCL3 (MIP-1α), and CXCL6 (huGCP-2), or murine chemokines CXCL1, CXCL2, and CXCL5." (PMID 30591657, 2018). "Still, even small wounds to the tumor created by needle biopsy can rapidly promote pro-inflammatory factors such as S100A8, CXCL2, CCL3, and COX2 followed by a significant increase in the number of myeloid derived suppressor cells in the tumor." (PMID 29728948, 2018). "It is notable that MDSCs infiltrating primary tumor lesions by sensing CXCL1, CXCL2, and CXCL5 promote epithelial-mesenchymal transition (EMT) and dissemination of cancer cells, by secreting TGF-β, EGF, and HGF." (PMID 30591657, 2018). "The migration of tumor-isolated MDSCs from HM-1-bearing mice was augmented by CXCL1 and CXCL2 in a dose-dependent manner." (PMID 29703902, 2018). "Previous work has shown that in PAFR KO animals with Ehrlich tumor ascites, elevated levels of CXCL2 and CCL2 chemokines controlled the recruitment of myeloid cells to the tumor." (PMID 29445756, 2017). "It is recruited to the tumour microenvironment by chemokines such as CXCL8,CXCL1,CXCL2, and CXCL3 by the production of inflammatory mediators such as TNF-Alfa, MIP-1 ALFA, H202, and NO that are cytotoxic to tumour cells." (PMID 28275390, 2017). "Expression of the CXCR2 ligands CXCL1 and CXCL2, known to be downstream of MAPK and NF-κB signaling, correlated with accumulation of CXCR2 positive gMDSC in the TME with tumor progression." (PMID 28915554, 2017). "We detected a concentration gradient for the CXCR2 ligands CXCL1, CXCL2, CXCL5, CXCL6 and CXCL8 between the plasma and the tumor tissues of patients with primary RCC." (PMID 28923105, 2017).
tumor (continued). "We next measured whole tumor RNA levels of the chemokine receptors CXCR2 and CSF1R as well as the cognate chemokines for these receptors, CXCL1/CXCL2 and CSF1, respectively." (PMID 28915554, 2017). "Several genes were up‐regulated in tumor tissues during the progression period, including CXCL1, CXCL2, CXCL3, and IL‐1β, while CXCR1 expression was down‐regulated." (PMID 27682863, 2016). "Specifically, the chemokine‐related genes, CXCL1, CXCL2, CXCL3, and IL‐1β, were up‐regulated, while CXCR1 was down‐regulated in tumor tissue during the progression of HCC." (PMID 27682863, 2016). "CXCL1, CXCL2, and CXCL3 expression was higher and CXCR1 expression was lower in tumor tissues during HCC progression compared with the controls." (PMID 27682863, 2016). "At the molecular level, impaired tumor growth in the three PDXs treated with p38 MAPK inhibitor correlates with downregulation of the chemokines CXCL-1 and CXCL-2 and the cytokine IL-6, which are all known to play key roles in colon tumorigenesis." (PMID 25890501, 2015). "Tumor-derived CXCR2-ligands (IL-8, CXCL1, CXCL2, and CXCL5) attract MDSCs to the tumor microenvironment and inhibition of CXCR2 profoundly suppresses Gr-1+ leukocyte migration into tumor." (PMID 26078490, 2015). "The continuous recruitment of neutrophils to the tumor site in response to the presence of neutrophil chemoattractants such as IL-8, CXCL-1 and CXCL-2 in the tumor microenvironment, make TAN capable of regulating tumor growth and metastasis." (PMID 26460736, 2015). "Conversely, KLF4, CXCL2, MAPK3 and TIMP4 were up regulated in normal samples compared to tumor tissues." (PMID 26498364, 2015). "Chemokines CXCL1, CXCL2 and CXCL12 have been proved to play important roles in the growth of various cancers by activating MAPK/ERK signaling pathway and thus promote tumor cell proliferation." (PMID 26313265, 2015). "GROβ (CXCL2) is a chemokine produced by endotoxin-treated macrophages that mediates inflammation and tumor development." (PMID 25944970, 2015). "Expression levels of multiple genes encoding for cytokines or cytokine receptors over-expressed in tumor cells or ascites fluid, such as CXCL1, CXCL2, CXCL3, IL8, IL6, IL6R, and CXCR4 were reduced in OV3/COX1KD cells." (PMID 25972361, 2015). "Tumor-derived CXCR2-ligands, CXCL1, CXCL2, and CXCL5, have been known to promote recruitment of MDSCs to the site of tumor or to the premetastatic niche." (PMID 26078490, 2015). "The anti-angiogenic (CXCL9, CXCL10) and pro-angiogenic markers (VEGFa, CXCL2, CXCL5, Angiopoietin 1 and Angiopoietin 2) were quantified in the tumor by RTQPCR." (PMID 22815789, 2012). "It must be noted however, that expression of many of the chemokines were most often found to be downregulated in the NSCLC tumours as follows CXCL1 (64.9%, p<0.01), CXCL2 (81.1%, p<0.01), CXCL3 (59.5%)." (PMID 21298036, 2011). "Densitometric analysis of the RT-PCR revealed a significant decrease in the expression of CXCL1, CXCL2 (p<0.01) and the CXCR1 receptor (p<0.05) in NSCLC tumour samples compared with normal." (PMID 21298036, 2011). "Breast cancer cells secrete much higher level of M-CSF, OSM, MIP-2/CXCL-2, MMP-9 and TIMP-1 than ES cells, which are factors correlated with tumor metastasis." (PMID 22174624, 2011). "Transcriptome analysis of purified tumor-infiltrating immune cells indicated that only PMN-MDSC express Il8rb (also known as CXCR2), the receptor for CXCL1, CXCL2, and CXCL5." (PMID 21980263, 2011). "For example, RAW 264.7 cells stimulated with tumor cell CB up-regulated several angiogenic factors (VEGF-A, HIF1α and TGF-β) and chemoattractants (CXCL12 and CXCL2)." (PMID 19696929, 2009). "Furthermore, transcription factors FOS and JUNB showed robust correlations with CXCL2 and HBEGF, suggesting multiple molecular mechanisms regulating tumor angiogenesis in Transitional Mono to M0 cells." (PMID 41514936, 2026).
tumor (continued). "Modulation of oral commensal bacteria and immune mediators such as IL-17–producing γδ T cells or CXCL2/CXCR2 could aid in monitoring OSCC progression and in developing adjunct therapies to mitigate tumor-promoting inflammation." (PMID 40924302, 2025). "Moreover, besides G-CSF there are other cytokines such as CXCL1 and CXCL2, which are also known for their ability to recruit PMN-MDSC cells from the circulation into the tumor stroma." (PMID 41226317, 2025). "It is worth mentioning that different CAF-derived factors such as CXCL2 and CXCL5 can also contribute to the expression of iICP receptors such as PD-L1 on tumor cells in a tumor-specific fashion, implying the involvement of a number of intracellular signaling mechanisms." (PMID 40805183, 2025). "CSCs activate the expression of the chemokines CXCL1, CXCL2, and CXCL8 through the ERK pathway, facilitating the recruitment of MDSCs within the tumor, whereas MDSCs help maintain the stem cell characteristics of cancer cells, promote angiogenesis, and assist in CSC metastasis and colonization." (PMID 41368628, 2025). "Similarly, KAT6A-catalyzed acetylation strengthens SMAD3 binding to the CXCL2 promoter, facilitating MDSC recruitment and tumor metastasis." (PMID 41303712, 2025). "Additionally, ENKTL tumor cells can express DPP4, which cleaves CXCL2, CXCL9, and CXCL10, chemokines that recruit T cells and NK cells into the tumor microenvironment, depleting the number of anti-tumor effector cells." (PMID 41295262, 2025). "Therefore, ERO1α+ tumor cells secrete G-CSF, which acts as a proliferation factor for PMN-MDSC cells as well as CXCL1 and CXCL2, which stimulate PMN-MDSC cells recruitment from the circulation into the tumor stroma." (PMID 41226317, 2025). "Notably, members of the CXC chemokine family, including CXCL1, CXCL2, CXCL3, CXCL5 and CXCL8, function through the activation of CXCR1 and CXCR2, playing a key role in promoting tumour angiogenesis." (PMID 39161078, 2025). "NE are actively recruited to the GBM microenvironment through chemotactic signals such as C-X-C motif chemokine ligands 1, 2 and 8 (CXCL1, CXCL2, and CXCL8) secreted by tumor cells, stromal cells, and infiltrating immune cells, allowing selective NE accumulation at the tumor site." (PMID 40006088, 2025). "CXCR2 ligands such as CXCL1, CXCL2, CXCL3, and CXCL5 are highly expressed in the tumor microenvironment of KRAS-mutant preclinical models, although their elevated secretion is often attributed to stromal or immune cells rather than direct production by KRAS-mutant tumor cells." (PMID 40524071, 2025). "In contrast, N2 TANs possess regular or circular nuclei and are induced by a wide array of tumor- and stroma-derived factors, including TGF-β, IL-6, IL-17, CXCL2, prostaglandin E2 (PGE2), granulocyte colony-stimulating factor (G-CSF), GM-CSF, and hyaluronic acid (HA) fragments." (PMID 40805288, 2025). "Specifically, the detection of the species Fusobacterium nucleatum, a constituent of this phylum, has been linked to increased expression of pro-inflammatory chemokines such as CXCL1, CXCL2, and CCL2, alongside enhanced angiogenesis and tumour gene expression alterations." (PMID 41516317, 2025). "Similarly, the increased recruitment of MDSCs by the expression of CXCL2 inhibits the action of CD8+ T cells and promotes tumour growth in ovarian cancer." (PMID 40852716, 2025). "When co-culturing CAR T cells with TB32043mb6s2 cells in vitro, a significant secretion of CXCL2, CXCL16 and CCL17 was observed, which are potentially tumour-promoting factors that could hinder therapeutic efficacy in vivo." (PMID 40361460, 2025). "Across multiple preclinical tumor models, RT has been shown to increase the expression of cytokines such as IL-1β, GM-CSF (CSF2), and G-CSF (CSF3), along with chemokines including CXCL1, CXCL2, CXCL5, CCL2, and CCL5." (PMID 40805288, 2025).
tumor (continued). "Interestingly, the scRNA‐seq data revealed the upregulation of CXCL2, CXCL3, CXCL8, and CCL4 in metastatic tumor cells compared to primary tumor cells or normal cells." (PMID 39985269, 2025). "Previous study showed that CAFs could mediate resistance to CSF-1R therapy by secreting CXCL1 and CXCL2 to recruit PMN-MDSCs, and the combined inhibition of CXCR2 and CSF-1R could overcome tumor resistance." (PMID 38291516, 2024). "Likewise, tumor cells and tumor-infiltrating CD11b+ myeloid cells can contribute to the high expression of CXCL1 and CXCL2, and deletion of CXCL1 and CXCL2 delays in vivo tumor growth." (PMID 39621069, 2024). "CXCL2, a neutrophil chemo-attractant that is involved in chronic inflammation and tumor progression, was identified as negative prognostic factor after CRT in peripheral blood." (PMID 38653773, 2024). "While S100A9, IL-10, and Cxcl2 expression was reduced in a-PD-L1-treated 2F8c tumors compared to tumor controls, no reduction was detected between a-PD-L1-treated and control Egfl6+ tumors." (PMID 39312740, 2024). "Tumor-educated MSCs can further activate and release the chemoprotective and immunomodulatory factors including CXCL1, CXCL2, and IL-8, favoring tumor progression in which MSCs generated CXCL2, VEGF, TGF-β, and IL-6 can further raise tumor aggressive phenotype by boosting tumor angiogenesis." (PMID 38951845, 2024). "Given the widespread role of CXC chemokines in oncogenesis, it was imperative to evaluate the possibility that CXCL2/12/14/17 could be differentially expressed in UCEC, potentially influencing the status of tumor microenvironment." (PMID 38232115, 2024). "Moreover, C-X-C-type chemokines including CXCL8 (IL-8), CXCL2, and CXCL12 secreted by CAFs are also involved in tumor proliferation by promoting angiogenesis and metastasis (CXCL8 & CXCL12) and increasing PD-L1 expression (CXCL2)." (PMID 38539448, 2024). "In vitro, Juz- or Gem/Juz-treated KPC tumor cells secreted significantly more macrophage-chemoattractant cytokines, e.g., CCL2, CCL20, and CXCL2, whilst Juz- and Gem/Juz-treated macrophages (MH-S) secreted cytokines of the M1 phenotype, e.g., IL6, TNF-α, and IL12." (PMID 39723364, 2024). "Furthermore, CXCL2, CXCL12, CCL2, and CXCL8 in humans have each been observed to regulate G-MDSC recruitment to the tumor microenvironment." (PMID 37988164, 2024). "Consistently, a series of chemokines, such as CCL2, CCL14, and CXCL2, as well as selectins were highly expressed in non-tumor–derived veins, whereas tumor-derived ones showed increased expression of genes related to collagen formation and ECM remodeling." (PMID 39345334, 2024). "Future studies will be necessary to define the functional significance and underlying mechanisms of other tumor supportive cytokines/chemokines (i.e., IL1A/B, LIF, G/M-CSF and CXCL2/3) and inflammatory proteins (i.e., S100P and S100A9) in mediating XIST regulation of tumor growth and CSC activity." (PMID 36922677, 2023). "Despite higher expression of Cxcl2, we saw no increase in tumour neutrophil recruitment (determined by percentage of Myeloperoxidase‐positive cells) when DKK1 was overexpressed in Nicd/Akt or KrasG12D/gTrp53 tumours." (PMID 35924447, 2023). "ROS also initiated the inflammatory reaction by the NF-κB pathway to secrete chemokines both in tumor cells and the tumor microenvironment, such as CCL2, CCL3, CXCL2, and CXCl12, which were upregulated by Se-PC PDT, and CCL24 and CXC17, which were downregulated by Se-PC PDT in the tumor niche." (PMID 37994159, 2023). "We also observed that MDSC-secreted VEGFA and multiple chemokines CCL2, CXCL1, CXCL2, CXCL3, and CXCL8 could act on endothelial cells via VEGFA-KDR/FLT1 and CCL2/CXCLs-ACKR1 interactions, which were crucial for tumor angiogenesis." (PMID 37475874, 2023).